RN7SKP137 (RN7SK pseudogene 137)
Gene: Miscellaneous RNA gene on chromosome 4 (121,061,172 to 121,061,478, reverse strand). Ensembl gene ENSG00000223006.
Homologues: Orthologues: chimpanzee 7SK (99% identical). Paralogues in human: RN7SKP255 (76% identical), RN7SKP9 (76% identical), 7SK (75% identical), RN7SKP203 (75% identical), RN7SKP74 (75% identical), RN7SKP80 (74% identical), RN7SKP79 (74% identical), RN7SKP90 (74% identical), RN7SKP176 (74% identical), RN7SKP6 (74% identical), RN7SKP211 (73% identical), RN7SKP71 (73% identical), and 283 more.